IGKV5-2 (immunoglobulin kappa variable 5-2)
Description:
V region of the variable domain of immunoglobulin light chains that participates in the antigen recognition. Immunoglobulins, also known as antibodies, are membrane-bound or secreted glycoproteins produced by B lymphocytes. In the recognition phase of humoral immunity, the membrane-bound immunoglobulins serve as receptors which, upon binding of a specific antigen, trigger the clonal expansion and differentiation of B lymphocytes into immunoglobulins-secreting plasma cells. Secreted immunoglobulins mediate the effector phase of humoral immunity, which results in the elimination of bound antigens. The antigen binding site is formed by the variable domain of one heavy chain, together with that of its associated light chain. Thus, each immunoglobulin has two antigen binding sites with remarkable affinity for a particular antigen. The variable domains are assembled by a process called V-(D)-J rearrangement and can then be subjected to somatic hypermutations which, after exposure to antigen and selection, allow affinity maturation for a particular antigen.
Synonyms: IGKV52; B2
Tractability: Antibody: its Gene Ontology location is reachable by antibodies, with high confidence; UniProt places it where antibodies can reach, with medium confidence; UniProt predicts a signal peptide or a membrane-spanning region.
Gene: Immunoglobulin variable (V) gene on chromosome 2 (88,897,232 to 88,897,784, forward strand). Ensembl gene ENSG00000211599.
Subcellular location: Secreted; Cell membrane
Pathways (Reactome):
Immune System: Antigen activates B Cell Receptor (BCR) leading to generation of second messengers; CD22 mediated BCR regulation; Classical antibody-mediated complement activation; FCERI mediated Ca+2 mobilization; FCERI mediated MAPK activation; FCERI mediated NF-kB activation; FCGR activation; Fc epsilon receptor (FCERI) signaling; Immunoregulatory interactions between a Lymphoid and a non-Lymphoid cell; Initial triggering of complement; Regulation of Complement cascade; Regulation of actin dynamics for phagocytic cup formation; Role of LAT2/NTAL/LAB on calcium mobilization; Role of phospholipids in phagocytosis
Disease: FCGR3A-mediated IL10 synthesis; FCGR3A-mediated phagocytosis; Potential therapeutics for SARS
Hemostasis: Cell surface interactions at the vascular wall
Vesicle-mediated transport: Scavenging of heme from plasma
Gene Ontology:
Molecular function: antigen binding
Biological process: immune response
Cellular component: extracellular region; immunoglobulin complex; plasma membrane
Homologues: Orthologues: mouse Igkv17-121 (63% identical), mouse Igkv17-127 (63% identical). Paralogues in human: IGKV1-33 (51% identical), IGKV1D-33 (51% identical), IGKV1-6 (50% identical), IGKV1D-8 (50% identical), IGKV6D-21 (50% identical), IGKV1-17 (50% identical), IGKV1-8 (50% identical), IGKV1-9 (50% identical), IGKV3-11 (50% identical), IGKV3D-7 (50% identical), IGKV6-21 (50% identical), IGKV1-12 (49% identical), and 81 more.